MEN1 (menin 1)
Diseases named in the same sentence as MEN1 in open-access papers (continued):
Sharing a sentence is not in itself a finding about the gene and the disease.
multiple endocrine neoplasia type 1 (continued). "The MEN1 syndrome has variable inter- and intra-familial expression, a high degree of penetrance and, in absence of treatment, MEN1 patients have earlier mortality." (PMID 35268848, 2022). "A 45-year-old Caucasian lady with a history of a pituitary prolactinoma and parathyroidectomy was diagnosed with multiple endocrine neoplasia type 1 (MEN1), with germline testing positive for menin; no family members were affected." (PMID 34706762, 2021). "For instance, patients with multiple endocrine neoplasia type 1 (MEN1) do not require such extensive nuclear medical imaging and would benefit from an abbreviated examination protocol." (PMID 33670457, 2021). "In accordance, the proportion of phenocopy within the sporadic patients fulfilling the criteria for clinical MEN1 syndrome (11 MEN1-positive sporadic patients and 37 MEN1-negative sporadic patients) was 77.1% (37/48)." (PMID 31044390, 2019). "The medical history of the patient described herein (multiglandular PHPT and multiple gastro–entero–pancreatic tumors) was consistent with the diagnosis of MEN1 syndrome, but unexpectedly, the genetic testing of the MEN1 gene gave a negative result." (PMID 25416039, 2015). "While biochemical tests have suggested a prevalence of the MEN1 syndrome at 0.01–0.175 per thousand, the incidence of the syndrome based on genetic testing of the MEN1 gene in a large population is not yet clear." (PMID 25594065, 2014). "Multiple endocrine neoplasia type 1 (MEN-1) was considered due to the pituitary, parathyroid, and pancreatic involvement of the patient's endocrinopathies, but genetic diagnostic testing ultimately identified no disease-associated sequence changes on analysis of the MENIN gene." (PMID 19356251, 2009).
pancreatic neuroendocrine tumor (128 papers, 2011 to 2026). Pancreatic endocrine tumor, also known as pancreatic neuroendocrine tumor (PNET), describes a group of endocrine tumors originating in the pancreas that are usually indolent and benign, but may have the potential to be malignant. "Genomic studies focusing on pancreatic NETs highlighted mutations in MEN1, DAXX, ATRX, and targets in mTOR pathway." (PMID 41483302, 2026). "Pancreatic neuroendocrine tumors (PanNETs) frequently exhibit loss or reduced expression of the tumor suppressor MEN1, a key regulator of tumor progression and DNA damage response (DDR)." (PMID 41972414, 2026). "Based on prior data, the most prevalent mutations in pancreatic neuroendocrine tumors include those in MEN1 (44%), DAXX/ATRX (43%) 17, 18, and genes related to the mTOR pathway." (PMID 41323792, 2025). "In MEN1, pancreatic neuroendocrine tumors (pNETs) are the second most common neoplasms after parathyroid adenomas, affecting 30-80% of patients, and are a leading cause of MEN1-related mortality." (PMID 41541958, 2025). "A common occurrence among pancreatic NETs and lung NETs is the presence of both sporadic and germline MEN1 mutations." (PMID 40026252, 2025). "Inactivating MEN1 mutations are the predominant genetic defect driving tumorigenesis in pancreatic NETs (pNETs)." (PMID 39336822, 2024). "Somatic mutations of MEN1 and the loss of heterozygosity of MEN1 occur in 45% and 30–70% of sporadic pancreatic NETs, respectively." (PMID 38539517, 2024). "In MEN1 patients, mortality rates linked to syndrome manifestations can reach up to 50%, with pancreatic endocrine tumors being the predominant cause of death." (PMID 39201946, 2024). "A single pediatric study in MEN1 (N = 80) revealed the following: a PHP rate of 80% and pancreatic NET rate of 35% and 35 underlying germline MEN1 pathogenic variants (and 3/35 of them were newly detected)." (PMID 38928056, 2024). "MEN1 pathogenic variants in exon 2, 9, and 10 are prone to a more aggressive pancreatic NET behavior." (PMID 38928056, 2024). "The presence of multiple hormonal secretion in pancreatic NETs among MEN1 patients is associated with improved survival, possibly due to routine screening." (PMID 39201946, 2024). "Somatic mutations in MEN1 have been previously identified in 44% of pancreatic NETs and were found in 13% of our patients with NEN, including 2 with pancreatic NET." (PMID 37966258, 2023). "Approximately 10–20% of all pancreatic NETs are associated with MEN1, and up to 90% of patients with MEN1 will develop pancreatic NETs during their lifetime." (PMID 37761922, 2023). "On the other hand, mutations in the von Hippel–Lindau (VHL) gene are associated with SCNs, and mutations in the multiple endocrine neoplasia 1 (MEN1) gene or loss of heterozygosity (LOH) are associated with pancreatic neuroendocrine tumors." (PMID 36832193, 2023). "Inactivating somatic mutations in ATRX, DAXX, and MEN1 represent the major mutations encountered in pancreatic NETs, but are much less frequent in their thoracopulmonary counterparts, indicating distinct site-dependent genetic pathways driving these tumors." (PMID 36690805, 2023). "MEN1 was originally identified as a tumour suppressor, and mutations of the MEN1 in humans have been associated with various endocrine tumours, including parathyroid hyperplasia, pituitary adenomas and islet cell tumours." (PMID 35968938, 2022). "Two individuals with an MEN1 variant from one family had a self-reported family history of a pancreatic neuroendocrine tumor." (PMID 35668420, 2022). "ATRX and MEN1 genes are both involved in chromatin remodelling and have been identified as the most frequent somatic mutation in pancreatic NETs." (PMID 35323929, 2022). "Among those different endocrine tumors of MEN1, the pancreatic neuroendocrine tumors (PNETs) are life-threatening and frequently implicated." (PMID 35954231, 2022).
pancreatic neuroendocrine tumor (continued). "Loss-of-function mutations of the multiple endocrine neoplasia type 1 (MEN1) gene are causal to the MEN1 tumor syndrome, but they are also commonly found in sporadic pancreatic neuroendocrine tumors and other types of cancers." (PMID 35941657, 2022). "Pancreatic endocrine tumors develop from beta islets, through a stage of islet hyperplasia in which the wild-type MEN1 allele is still retained." (PMID 34298972, 2021). "Advances in tumor genetic profiling of pNETs have identified somatic MEN1 mutations in 30–44% of sporadic islet cell tumors." (PMID 33716975, 2021). "Pbk is upregulated in Men1‐excised islets in mouse models and in human pancreatic neuroendocrine tumor (PNET) tissues with MEN1 loss‐of‐function mutations." (PMID 33821572, 2021). "In our study, we demonstrate that AtT20 cells express the BET family members Brd2, Brd3 and Brd4, with Brd2 being the most abundant, which is similar to data reported for MEN1-associated mouse pancreatic NETs and human pancreatic and bronchial NET cell lines." (PMID 31935194, 2020). "Pancreatic NET also exhibit recurrent mutations in a relatively limited number of genes, including the tumor suppressor gene MEN1, as well as ATRX and DAXX, genes implicated in chromatin remodeling." (PMID 32477464, 2020). "Conversely, inactivating mutations in DAXX and ATRX and in MEN1 are exclusively found in pancreatic NET." (PMID 32492939, 2020). "MEN1 is another tumor suppressor gene frequently inactivated in pancreatic NET, and we previously observed that double loss of heterozygosity (LOH) of PHLDA3 and MEN1 frequently occurs in pancreatic NET8,9." (PMID 30787304, 2019). "Menin is encoded by multiple endocrine neoplasia type 1 (MEN1) gene, the germ line mutations of which are the main cause of pancreatic neuroendocrine tumors (PNETs)." (PMID 31652443, 2019). "MEN1 is an autosomal dominant syndrome, the most common among the four, and causes pancreatic NETs through an inactivating mutation in MEN1, which encodes menin." (PMID 29590641, 2018). "Pancreatic neuroendocrine tumors are also characterized by recurrent mutations in a relatively limited number of genes, which include tumor suppressor gene MEN1, as well as ATRX and DAXX, genes implicated in chromatin remodeling." (PMID 28903345, 2017). "One patient with MEN1 gene: c.628_631delACAG mutation had grade 3 pancreatic NET (Ki-67 25%) with high MGMT expression, but still derived benefit from CAPTEM therapy with stable disease burden for 3 years after completion of 8 cycles." (PMID 29262620, 2017). "A second patient with MEN1 G74fs*45 mutation had grade 1 pancreatic NET had a dramatic response to CAPTEM with 45% response in target lesions." (PMID 29262620, 2017). "Insulinoma, one of the pancreatic neuroendocrine tumors (NETs) of MEN1, causes obvious symptoms even small in size due to hypoglycemia and is usually found small (less than 2.0 cm) at diagnosis." (PMID 27572829, 2016). "CDK1B mutation was identified only in small intestinal NET, whereas MEN1 mutation was identified in pancreatic NET." (PMID 26684240, 2016). "CDKN1B mutation was found in five cases of small intestinal NET, whereas MEN1 mutation was found in five cases of pancreatic NET." (PMID 26684240, 2016). "This revealed that approximatley 3% of these patients with MEN1-associated tumors, such as parathyroid adenomas, pituitary adenomas and pancreatic NETs in association with gonadal, adrenal, renal and thyroid tumors have CDNK1B mutations." (PMID 23933118, 2014).
pancreatic neuroendocrine tumor (continued). "A germline MEN1 mutation, which is also often detected in sporadic pancreatic neuroendocrine tumors, can lead to the development of familial MEN1 in an autosomal dominant fashion." (PMID 25594065, 2014). "Recently, somatic inactivating mutations in MEN1 have been also reported in 44% of pancreatic neuroendocrine tumors." (PMID 22825745, 2012). "Inactivating mutations in the MEN1 gene predisposing to the multiple endocrine neoplasia type 1 (MEN1) syndrome can also cause sporadic pancreatic endocrine tumors." (PMID 22666422, 2012). "In lung NETs, the identification of a somatic MEN1 mutation correlates with a poorer prognosis, though it may be indolent in α-like and sporadic pancreatic NETs with isolated MEN1 deficiency." (PMID 40026252, 2025). "When combined with a DAXX or ATRX mutation, MEN1-inactivated pancreatic NETs have a poor prognosis." (PMID 40026252, 2025). "Furthermore, the subject presented multiple cutaneous collagenomas from many years, which have 50–65% sensitivity and 92–100% specificity for MEN1, but with increased diagnostic performance in combination with pancreatic endocrine tumors." (PMID 38294658, 2024). "Also parathyroid adenomas are included in the NET; in fact in patients with MEN1, they showed a common pathogenic origin with gastro-entero-pancreatic NET and pituitary adenomas." (PMID 36998475, 2023). "As the malignant pancreatic NET is an important cause of death for MEN1 patients, the farther might have been a gene carrier; however, genetic information was not available." (PMID 34160414, 2021). "Thus, our data on PCs are in agreement with previous observations in pancreatic endocrine tumors in which a strong association between MEN1 variants and cytoplasmic localization of menin were observed." (PMID 22825745, 2012). "The hypermethylation of promoters of TSGs following the loss of menin can be regarded as a common pro-oncogenic epigenetic change in MEN1-related pancreatic neuroendocrine tumors, and, similarly, it could also occur in MEN1-gene-loss-driven parathyroid tumorigenesis." (PMID 39519139, 2024). "The novelty of the present report relies on the association between the MEN1 pathogenic variant (NM_130799.2):c.758delC (p.Ser253Cysfs*28) in exon 4 and a clinical phenotype characterized by pHPT, non-functioning pituitary microadenoma, left adrenal adenoma and multifocal pancreatic NETs." (PMID 39309708, 2024). "In line with literature data, our study confirms that in patients with pancreatic NETs, the co-occurrence of other MEN1 manifestations, such as primary hyperparathyroidism and pituitary adenoma, is a strong predictive feature for damaging variants in MEN1 gene." (PMID 37761922, 2023). "MEN1 is a rare autosomal dominant condition (prevalence 3–20/100,000) resulting from mutations in the tumor suppressor gene MEN1 and characterized by various neuroendocrine tumors such as parathyroid hyperplasia, pancreatic endocrine tumors, and pituitary adenomas." (PMID 37929040, 2023). "Sporadic pancreatic neuroendocrine tumors (pNETs) with wild type MEN1 represent a major yet largely ignored subset whose biology and metastatic potential remain poorly understood." (PMID 41573907, 2026). "There is an unmet need for biomarkers in multiple endocrine neoplasia type 1 (MEN1)-related pancreatic neuroendocrine tumors (PanNETs) that allow prediction of clinical behaviour and metastatic potential." (PMID 40581735, 2026). "The use of endoscopic ultrasound (EUS) in ZES/MEN1 is controversial because it detects <50% of duodenal lesions but is the most sensitive modality for detecting pancreatic NETs or pancreatic gastrinomas (the latter occurring in <5–20%)." (PMID 41463062, 2025).
pancreatic neuroendocrine tumor (continued). "The authors also found that pancreatic NETs exhibit recurrent genetic inactivation of MEN1, ATRX, and DAXX and the activation of the PI3K/mTOR pathway." (PMID 40026252, 2025). "Of note, a recent survey in 56 ENETS centers of excellence demonstrated that a majority, i.e. 69% of the centers still use CgA and 38% PP in the screening of duodeno-pancreatic NETs in patients with MEN1." (PMID 40455177, 2025). "Pancreatic NETs frequently exhibit changes in genes such as MEN1, DAXX, ATRX, TSC1, TSC2, CDKN1A, and CDKN1B, along with alterations in CDKN2A and SETD2 in metastatic lesions." (PMID 41426335, 2025). "Relying on more sensitive imaging modalities, current studies prove that non‐functioning pancreatic neuroendocrine tumors (NF‐pNETs) are the second most common tumor manifestation in MEN1 patients, which contribute significantly to premature death." (PMID 40170567, 2025). "Typically, patients with MEN1 were reported to develop hyperparathyroidism; pancreatic NETs (NF-pNEN > gastrinoma > insulinoma >> other); and pituitary adenomas." (PMID 41463062, 2025). "Endoscopic ultrasound (EUS) examination is the most sensitive imaging procedure for the detection of small (≤10 mm) pancreatic endocrine tumors in asymptomatic individuals with MEN1." (PMID 39336996, 2024). "In a recently presented study, a genomic signature of MEN1 mutation and DAXX-wild type correlated with longer PFS for pancreatic NET after capecitabine/ temozolomide treatment." (PMID 38909137, 2024). "The patient was diagnosed with MEN1, as he also possessed a pancreatic neuroendocrine tumor and parathyroid tumor, and because his father had been found to have MEN1." (PMID 38200366, 2024). "The most frequent tumor response to SSAs is stable disease, but an objective response can be observed, more frequently by using high-dose schedules and in MEN1-related pancreatic NETs." (PMID 37581846, 2024). "Here, we demonstrated that combined loss of MEN1, ATRX, and PTEN, tumor suppressors commonly mutated in human PanNETs, triggers the development of high-grade pancreatic neuroendocrine tumors in mice." (PMID 38609433, 2024). "Next, we found that mutations in MEN1, PTEN and ATRX or DAXX co-occur with a high statistical likelihood, suggesting that co-mutation of those genes is one of the core determinants of pancreatic neuroendocrine tumors pathogenesis." (PMID 38609433, 2024). "The second most frequent manifestation of adult MEN1 patients is pancreatic NETs; however, it is the rarest in young patients." (PMID 39336996, 2024). "MEN1 is characterized by the combined occurrence of parathyroid, pituitary and pancreatic neuroendocrine tumors, whereas MEN2 features medullary thyroid cancer in association with phaeochromocytoma and parathyroid tumors." (PMID 38884084, 2024). "MEN1-related pancreatic NETs appear as optimal candidate to SSA therapy even at localized non-metastatic stage." (PMID 37581846, 2024). "Studies in sporadic NENs have reported few recurrently mutated genes: MEN1 (20%) and ARID1A (8%) in lung NETs, MEN1 (40%) and ATRX/DAXX (35%) in pancreatic NETs and CDKN1B (10%) in small intestine NETs." (PMID 36795001, 2023). "Certain mutations in KLKB1, mutated in one of five CT-pNENs, cause prekallikrein deficiency, and KLKB1 was mutually exclusive with ATRX, DAXX, and MEN1 of pancreatic neuroendocrine tumors (PanNets)." (PMID 37771441, 2023). "The association of pancreatic NET with primary hyperparathyroidism and/or pituitary adenoma and pituitary- or NET-related endocrine syndrome was predictive of MEN1, while the association with adrenal tumors, meningiomas, and skin lesions was not predictive." (PMID 37761922, 2023). "Out of 110 patients with ZES, 48 patients had MEN1, while 62 subjects had sporadic pancreatic endocrine tumors." (PMID 36428828, 2022). "Pulmonary NETs usually harbor mutations in MEN1, PIK3CA, ARID1A, or KRAS, while pancreatic NETs often display MEN1, DAXX, ZFHX3, or ATRX aberrances." (PMID 35565339, 2022).